CNTF (ciliary neurotrophic factor)
Diseases named in the same sentence as CNTF in open-access papers (continued):
Sharing a sentence is not in itself a finding about the gene and the disease.
metabolic syndrome (1 paper, 2022). A cluster of metabolic risk factors for CARDIOVASCULAR DISEASES and TYPE 2 DIABETES MELLITUS. "Further insights into the metabolic role of endogenous CNTF in homeostatic and pathological conditions and of its sources, target cells and signalling pathways are expected to provide a better understanding of the pathophysiology of metabolic syndrome and improve treatment." (PMID 35585213, 2022).
obstructive sleep apnea (1 paper, 2023). "Other targeted pathways reported for the effects of A. graveolens in neurological disorders include Nrf2 and NF-κB pathways; BDNF/ERK/mTOR (antidepressant); CNTF/CNTFRa/JAK2/STAT3 (cerebral blood flow decreases); and SIRT1/PGC-1a (obstructive sleep apnea)." (PMID 37570794, 2023).
overnutrition (1 paper, 2019). An imbalanced nutritional status resulting from excessive intake of nutrients. "Moreover, neurotrophic factors as BDNF, ciliary neurotrophic factor (CNTF), and glial cell-derived neurotrophic factor (GDNF) regulate adult neurogenesis in multiple stages of NSC maturation and their expression is affected by overnutrition and metabolic stress." (PMID 31417349, 2019).
peripheral nerve injury (1 paper, 2014). Injury to a peripheral nerve. "We chose three IL-6-type cytokines IL-6, CNTF, and LIF because these three factors are known as “injury factors” that are induced after peripheral nerve injury and have been studied regarding their effects on CNS regeneration." (PMID 25162623, 2014).
primary ciliary dyskinesia (1 paper, 2017). A rare, genetically heterogeneous, primarily respiratory disorder characterized by chronic upper and lower respiratory tract disease. "Similarly, we find multiple genes involved in ciliopathies to be accelerated, including ‘deleted in primary ciliary dyskinesia’ (Dpcd), Iqcb1 (a component of primary cilia), and ciliary neurotrophic factor (Cntf)." (PMID 29035697, 2017).
primary open-angle glaucoma (1 paper, 2025). "Another promising approach for continuous intraocular delivery involves the NT-501, an ECT implant meticulously engineered for the sustained and continuous delivery of CNTF directly to the retina for therapy of primary open-angle glaucoma (POAG)." (PMID 41157282, 2025).
prostate carcinoma (1 paper, 2022). A carcinoma that arises from epithelial cells of the prostate gland. "We affirm that CNTF has a pivotal role in the prostate-cancer environment remodeling and suggest that this cytokine may be viewed as a modulator of invasion processes." (PMID 36497399, 2022). "Interleukin-6 (IL-6) has been established as a driver of prostate carcinogenesis and tumor progression while less is known about the role of ciliary neurotrophic factor (CNTF), a member of the IL-6 cytokine family in prostate cancer." (PMID 36497399, 2022). "IL-6 plays a key role in prostate cancer but no data on ciliary neurotrophic factor (CNTF), a member of interleukin-6 cytokine family, are known." (PMID 36497399, 2022).
rectal adenocarcinoma (1 paper, 2025). "Our study shows that multiple immune genes associated with ASCC3, including JAK1, NFKB1, SEMA5A, NR2C2, CNTF and CREB1, positively impact the prognosis of rectal adenocarcinoma patients." (PMID 40881169, 2025). "ASCC3 is a specific protective factor for rectal adenocarcinoma across various cancer types, particularly in digestive system cancers, and can synergize with several immune-related genes, including JAK1, NFKB1, SEMA5A, NR2C2, CNTF, and CREB1, to influence patient prognosis." (PMID 40881169, 2025).
rectal cancer (1 paper, 2025). A primary or metastatic malignant neoplasm that affects the rectum. "The combination of ASCC3 with several immune-related genes, including JAK1, NFKB1, SEMA5A, NR2C2, CNTF and CREB1, plays a significant predictive role in the prognosis of rectal cancer patients." (PMID 40881169, 2025). "Additionally, our diagnostic and prognostic models, constructed using machine learning, highlight the significant predictive value of ASCC3 in combination with various immune-related genes, including JAK1, NFKB1, SEMA5A, NR2C2, CNTF and CREB1, for rectal cancer prognosis." (PMID 40881169, 2025).
retinal dystrophies (1 paper, 2020). "For instance, continuous delivery of CNTF to the retina of rhodopsin-deficient mice conferred lifelong protection to a significant fraction of cone photoreceptors and prevented the loss of cones over a time period of up to ~ 3 years in patients with hereditary retinal dystrophies." (PMID 32932933, 2020).
rhabdomyosarcoma (1 paper, 2009). A rare aggressive malignant mesenchymal neoplasm arising from skeletal muscle. "Inhibition of FGFR3 signalling or activation of CNTF signalling might thus be a good candidate for anti-cancer stem cell therapy for rhabdomyosarcoma." (PMID 19888223, 2009).
Stuve-Wiedemann syndrome (1 paper, 2023). "Abbreviations: SWS = Stuve-Wiedemann syndrome, IVCM = in vivo confocal microscopy, CNTF = ciliary neurotrophic factor, BCVA = best corrected visual acuity, LIFR = Leukemia Inhibitory Factor Receptor, IGF1 = Insulin-like growth factor-1." (PMID 38239413, 2023).
type-2 diabetes (1 paper, 2020). "Recombinant CNTF has undergone clinical trials previously to treat type-2 diabetes, however the trials were halted due the potential immunogenicity of recombinant CNTF." (PMID 32765502, 2020).
neurodegenerative disease (17 papers, 2009 to 2023). A disorder of the central nervous system characterized by gradual and progressive loss of neural tissue and neurologic function. "CNTF is one of the most important neurotrophic factors involved in cell survival, and it has the potential to prevent neurodegenerative diseases." (PMID 36242717, 2023). "In summary, the findings of this study have revealed cellular responses of the neural retina to CNTF treatments, thus suggesting potential therapeutic treatments for neurodegenerative diseases." (PMID 36396639, 2022). "Many previous studies have demonstrated that expression-level changes in specific NTFs, such as BDNF, CNTF, and glial cell line-derived neurotrophic factor (GDNF), are associated with the pathogenesis of neurodegenerative diseases, such as AD, PD, HD, and ALS." (PMID 33802760, 2021). "In addition, they have been found to produce NTFs such as GDNF and CNTF in animal models of neurodegenerative diseases." (PMID 32188096, 2020). "Many studies have suggested that alterations in the levels of specific neurotrophic factors (NTFs), such as brain-derived neurotrophic factor (BDNF) and ciliary neurotrophic factor (CNTF), are associated with the pathogenesis of neurodegenerative diseases such as AD and Parkinson’s disease (PD)." (PMID 31766645, 2019). "Cumulative data from preclinical studies show the utility of BDNF and CNTF for conferring various neuroprotective effects led to the idea that these NTFs could be a clinically applicable therapeutic target in neurodegenerative diseases." (PMID 31766645, 2019). "Ciliary neurotrophic factor (CNTF) is an important motor neuron trophic factor that promotes neuronal survival and has a potential therapeutic role in neurodegenerative diseases." (PMID 35222082, 2022). "Some NTFs such as BDNF, CNTF, and GDNF are promising candidates for future treatment as they affect the glial activation status and have a beneficial effect on the outcomes of neurodegenerative diseases." (PMID 33802760, 2021). "Although the Rheb–mTOR signaling pathway may act as a double-edged sword in neurodegeneration, it is a central regulator of NTFs such as BDNF, CNTF, and GDNF and thus is a potential therapeutic target for neurodegenerative diseases." (PMID 32188096, 2020). "Neuroregulatory cytokines such as interleukin-6 (IL-6), ciliary neurotrophic factor (CNTF), leukemia inhibitory factor (LIF), cardiotrophin-1 and cardiotrophin-2 (CT-1 and CT-2), oncostatin-M and neuropoietin are useful in the treatment of neurodegenerative diseases and trauma." (PMID 35833035, 2022).
cancer (10 papers, 2004 to 2025). A tumor composed of atypical neoplastic, often pleomorphic cells that invade other tissues. "The CNTF-triggered retinal metabolic changes show striking similarities to the metabolic signatures of cancer cells as described by Warburg nearly a century ago75." (PMID 36396639, 2022). "In Kaplan–Meier analyses, only IL6 (p = 0.036) showed a significant association with cancer-specific survival, whereas CRP (p = 0.075) and CNTF (p = 0.084) demonstrated borderline values." (PMID 33066437, 2020). "For this experiment, we used the reactive SF268 astrocyte cancer cell line by ciliary neurotrophic factor (CNTF, 50 ng/ml, 4 days) treatment." (PMID 31427599, 2019). "Furthermore, we analyzed the mutation status of ASCC3, JAK1, NFKB1, SEMA5A, NR2C2, CNTF and CREB1 across pan-cancer." (PMID 40881169, 2025). "In addition, we demonstrated that CNTF downregulated MMP-2 expression which is the main MMP involved in cell cancer invasiveness." (PMID 36497399, 2022). "Moreover, MAPK/ERK, AKT/PI3K and Jak/STAT pathways that regulate proliferative, invasive and glucose-uptake processes in cancer progression are triggered by CNTF." (PMID 36497399, 2022). "Moreover, given the well-described role of CNTF-induced differentiation in healthy cells, we suspect that CNTF-induced cell cycle arrest in iSCs likely takes advantage of differentiation-induced cell cycle arrest, which has for a long time been a promising avenue to treat cancer." (PMID 30364248, 2018). "Circulating concentrations of CNTF and LIF were less than the detection limit of the assay in all healthy subjects and cancer patients." (PMID 15570310, 2004).
tumor (10 papers, 2013 to 2026). "Oncostatin M (OSM) exhibits tumor-promoting properties, whereas ciliary neurotrophic factor (CNTF) induces dormancy." (PMID 41596432, 2026). "More studies are clearly required to corroborate our data, as in vivo male murine studies concerning allographic transplantation of 22Rv1 cells in CNTF-treated and -untreated conditions to evaluate the CNTF effect in tumor growth and metastasis inhibition." (PMID 36497399, 2022). "IL-6 has been established as a driver of carcinogenesis and tumor progression in PCa, while less is known about the role of ciliary neurotrophic factor (CNTF), a member of IL-6 type cytokine family." (PMID 36497399, 2022). "Together, these experiments provide evidence for a tumor suppressive endoneurial niche that functions to repress proliferation and identifies CNTF signaling as a potential therapeutic avenue for MPNST." (PMID 30364248, 2018). "CNTF and PIF are tumor-derived molecules that also induce protein degradation in skeletal muscle through the induction of the ubiquitin-proteasome proteolytic pathway." (PMID 40430444, 2025). "It has been previously established that LIFR expression on breast cancer cells promotes tumor dormancy in the bone marrow and that several of the gp130 cytokines (LIF, OSM, and CNTF) are able to signal through LIFR." (PMID 32023849, 2020). "Several other ligands (OSM and CNTF included) are also able to bind to LIFR, which may mediate the tumor-suppressive actions of LIFR." (PMID 32023849, 2020). "This study also noted that several gp130 cytokines (IL-6, LIF, CT-1, and CNTF) were able to significantly increase the CSC population in HMECs, pointing to their potential role as microenvironmental cytokines capable of promoting tumor progression through STAT3." (PMID 32023849, 2020).
neurological disorders (6 papers, 2010 to 2025). "Considering the heterogeneity of cell types expressing CNTF and the widespread expression of its receptors in the nervous system, CNTF remains a potential therapeutic target for neurological disorders." (PMID 37692101, 2023). "This study also opens up avenues for pharmacologically stimulating and utilizing the neuroprotective actions of endogenous CNTF in neurological diseases, thus circumventing the low CNS bioavailability and systemic side effects of systemic administered CNTF." (PMID 23693126, 2013). "Our findings further validate CNTF overexpression as a neuroprotective strategy for the treatment of HD and other neurological diseases characterized by glutamate-mediated neurodegeneration." (PMID 20062544, 2010). "Our results not only reveal tryptase as a potent factor to regulate TGF-β and CNTF production in astrocytes but may also provide a novel therapeutic option to neurological disorders." (PMID 23818741, 2013). "Modulating neurotrophins—the brain-derived neurotrophic factor (BDNF), glial cell line-derived neurotrophic factor (GDNF), and ciliary neurotrophic factor (CNTF)—support neurogenesis, neuroprotection, and synaptic plasticity in neurologic disorders." (PMID 40943142, 2025).
retinopathy (4 papers, 2016 to 2022). "The results from this study provide evidence for changes in the expressions of BDNF, CNTF, and FGF-2 in Oxygen-induced retinopathy." (PMID 36532277, 2022). "This study provides evidence for changes in BDNF, CNTF, and FGF-2 in Oxygen-induced retinopathy." (PMID 36532277, 2022). "Moreover, the interaction between EP300 and STAT3 is increased by treatment with CNTF or FGF2, suggesting a possible mechanism whereby CNTF and FGF2 reduce apoptosis and protect photoreceptor cells from light-induced retinopathy." (PMID 27242532, 2016).
infection (2 papers, 2018). The state of being infected such as from the introduction of a foreign agent such as serum, vaccine, antigenic substance or organism. "Activation of STAT3 with cytokines such as CNTF or LIF decreases rod generation, and infection of ex vivo retinas with a dominant negative form of STAT3 prevents basal or CNTF-stimulated inhibition of photoreceptor development." (PMID 30364083, 2018). "Based on previous studies in the visual system, we propose that the mechanisms of protection and promotion of plasticity and regenerative capacity are mediated and amplified both by direct infection of CSN themselves but also due to bystander release of CNTF by adjacent nonprojecting cortical cells." (PMID 30245710, 2018).
psychiatric disorder (2 papers, 2015 to 2024). A disorder characterized by behavioral and/or psychological abnormalities, often accompanied by physical symptoms. "A number of studies demonstrate that impaired CNTF signaling caused by mutations in the genes of the receptor complex CNTFR*gp130 (CNTFR and IL6ST genes, respectively) may contribute to mental disorders." (PMID 38646100, 2024). "The role of CNTF in the pathogenesis of psychiatric disorders has not been elucidated." (PMID 38646100, 2024).
metabolic disease (1 paper, 2023). A congenital disorder (due to inherited enzyme abnormality) or acquired (due to failure of a metabolically important organ) disorder resulting from an abnormal metabolic process. "CNTF can also regulate the survival and/or differentiation of many cell types, including neurons, adipocytes, oligodendrocytes, muscle cells, bone cells, and retinal cells; thus, it is widely used in treating neurodegenerative and metabolic diseases." (PMID 36266504, 2023).
CNTF also shares sentences with these, for which no sentence is quoted: geographic atrophy (3 papers); brain diseases (2); cold-induced sweating syndrome (2); macular degeneration (2); peripheral neuropathies (2); age-related macular degeneration (1); atherosclerosis (1); autism spectrum disorder (1); bacterial infections (1); cardiomyopathy (1); cognitive decline (1); cognitive disorder (1); COVID-19 (1); cyst (1); delirium (1); digestive system cancer (1); Down syndrome (1); Dyskinesia (1); dyslipidaemia (1); Gliosis (1); Glucose intolerance (1); heart disease (1); immune disorders (1); inflammation (1); late infantile neuronal ceroid lipofuscinosis (1); lysosomal storage disorder (1); neuronal ceroid lipofuscinosis (1); neurotoxicity (1); non-small cell lung carcinoma (1); pancreatic cancer (1).
A further 5 diseases each share a sentence with CNTF in 1 paper.